LNCROPM (lncRNA regulator of PLAAT3 mediated phospholipid metabolism)
Gene: Long non-coding RNA gene on chromosome 11 (63,616,293 to 63,658,962, forward strand). Ensembl gene ENSG00000256789.
Diseases named in the same sentence as LNCROPM in open-access papers:
LNCROPM is named in the same sentence as 4 diseases in open-access papers, as found by Europe PMC text mining. Sharing a sentence is not in itself a finding about the gene and the disease. The quoted sentences say what the papers report.
cancer (1 paper, 2021). A tumor composed of atypical neoplastic, often pleomorphic cells that invade other tissues. "Interestingly, by analyzing TCGA database, we also found that lncROPM had important functions in other cancers." (PMID 34715882, 2021).
LNCROPM also shares sentences with these, for which no sentence is quoted: breast tumors (1 paper); head and neck squamous cell carcinoma (1); ovarian serous cystadenocarcinoma (1).